WNT1 (Wnt family member 1)
Diseases named in the same sentence as WNT1 in open-access papers (continued):
Sharing a sentence is not in itself a finding about the gene and the disease.
mammary adenocarcinomas (11 papers, 2006 to 2025). "Transgenic expression of Wnt1 using a mouse mammary tumor virus LTR enhancer causes extensive ductal hyperplasia early in life and mammary adenocarcinomas in approximately 50% of the female transgenic (MMTV-Wnt1) mice by 6 months of age." (PMID 38590657, 2024). "Investigations into the latency and incidence of mammary adenocarcinomas in Wnt1-transgenic mice determined that roughly 80% of mice had developed tumors by 7 months of age, similar to our findings." (PMID 39969175, 2025). "Atypical Wnt1 expression under the mammary tumor virus promoter (MMTV-Wnt1) within Wnt1-transgenic mice induces mammary adenocarcinomas." (PMID 39969175, 2025). "The relationship between Wnt signaling and cancer was discovered in the 1980s when the proto-oncogene Int1 (Wnt1) was shown to induce mammary adenocarcinoma in mice." (PMID 32824859, 2020). "Female mice that express Wnt1 under the mammary-specific MMTV promoter reproducibly develop mammary adenocarcinomas within one year." (PMID 19503830, 2009). "To compile a model-independent systematic analysis of the tumor immune effects of the obese environment, we investigated five syngeneic cell line tumor models in two cancer types (mammary adenocarcinoma: E0771, TeLi and Wnt1; pancreatic ductal adenocarcinoma: C11 and UN-KC)." (PMID 33653826, 2021).
prostate carcinoma (11 papers, 2008 to 2025). A carcinoma that arises from epithelial cells of the prostate gland. "To further elucidate how the active ingredients in XHP regulate the Wnt pathway and influence prostate cancer proliferation, we conducted molecular docking using LC-MS/MS-identified active compounds as ligands and the key target protein, Wnt1, as the receptor." (PMID 38994113, 2024). "As expected, expression of Wnt1 in the prostate cancer cells PC3, CWR22Rv1 and LNCaP resulted in the activation of the luciferase reporter gene driven by a LEF-dependent promoter." (PMID 18218096, 2008). "This study suggests that XHP might act as a Wnt inhibitor, affecting the expression of β-Catenin and Wnt1 proteins to modulate prostate cancer cell activity." (PMID 38994113, 2024). "Also, previous studies show that expression of Wnt-1 and β-catenin is increased in invasive PCa cell lines and in primary prostate cancer specimens." (PMID 34108600, 2021). "Wingless-related MMTV integration site 1 or Wnt-1 occurs in shallow quantity in primary prostate epithelial cells but it has been observed that it is up-regulated in prostate cancer cell lines and tissues, especially in the lymph node and bone metastases samples." (PMID 35201496, 2021). "Consistent with this was the observation that Wnt1 plays a role in the regulation of CD36 via activation of the canonical Wnt pathway, and that CAV expression is closely associated with Myc in prostate cancer." (PMID 28798698, 2017). "Overexpression of Wnt1 was found in the majority of prostate carcinoma specimens." (PMID 23469146, 2013). "Whereas in prostate cancer RLX promotes tumor progression via its effects on the protocadherin PCDHY18, the effects we described are mediated, at least in part, by increased expression of Wnt1 and reduced expression of Dkk1." (PMID 31811156, 2019).
ovarian carcinoma (9 papers, 2014 to 2025). A malignant neoplasm originating from the surface ovarian epithelium. "Meanwhile, we found that the high expression of FBXO45 in ovarian cancer tissues was accompanied by a corresponding elevation of WNT1 protein in clinical samples of 3 ovarian cancer tissues and normal ovarian tissues." (PMID 40990020, 2025). "KRAS and IGF1 are the top activated signaling, along with WNT1 inhibited, in immunotherapy responded ovarian cancer." (PMID 34921236, 2021). "Compared with the frequency of Wnt1 expression in ovarian cancer, Wnt5a was more frequently found in malignant epithelial ovarian cancer patients (80% out of a total 38)." (PMID 28491097, 2017). "Of note, patients with ovarian cancers that express high levels of both Wnt1 and Wnt5a had a significantly lower probability of long-term survival than patients with ovarian cancers that did not express Wnt1 or Wnt5a." (PMID 28491097, 2017). "In ovarian carcinoma, abnormal expression of β-catenin, E-cadherin and WNT-1 was observed, but their prognostic and predictive role is unclear." (PMID 24499657, 2014). "WNT-1 expression has been detected in ovarian carcinomas; however, other WNT ligands were also found such as WNT-5a, which was highly expressed in EOC tumours." (PMID 24499657, 2014). "H19/miRNA-140 axis promotes ovarian cancer cell migration by upregulating Wnt1 expression." (PMID 36310592, 2022). "In addition, silencing miR-361-3p was significantly promoted the Wnt1 protein expression and β-catenin nuclear expression, indicating that miR-361-3p inhibited Wnt/β-catenin signaling pathway in ovarian cancer." (PMID 34116704, 2021). "The aim of this study was to determine the expression of β-catenin, E-cadherin and WNT-1 in advanced epithelial ovarian cancers and to assess the correlation of expression of the studied proteins with patient survival and response to platinum-based chemotherapy." (PMID 24499657, 2014). "In ovarian cancer, intense expression of E-cadherin, β-catenin and WNT-1 was found." (PMID 24499657, 2014). "Additionally, aberrant expression of β-catenin, E-cadherin and WNT-1 was observed in ovarian carcinoma." (PMID 24499657, 2014). "On the other hand, in the case of ovarian cancer patients, Wnt1 expression (HR = 0.9; P = 0.15) was thought to have no such effects." (PMID 36056132, 2022). "The results showed that LINC00922 knockdown was significantly decreased the Wnt1 protein expression and β-catenin nuclear expression in SKOV-3 and ES-2 cells compared with those in the control group, indicating that LINC00922 activated Wnt/β-catenin signaling pathway in ovarian cancer." (PMID 34116704, 2021).
gastric tumor (8 papers, 2009 to 2023). "We also showed that GRA treatment upregulated miR-149-3p expression, which inhibited cell cycle progression and induced cell apoptosis in gastric tumor cells by suppressing the expression of its direct target gene Wnt-1." (PMID 27713126, 2016). "To further investigate the expression locations of COX-2, Wnt-1 and β-catenin, we analyzed immunohistochemically stained gastric tumor tissue." (PMID 27713126, 2016).
renal fibrosis (8 papers, 2021 to 2024). A final common manifestation of a wide variety of chronic kidney diseases characterized by glomerulosclerosis and tubulointerstitial fibrosis. "Of all Wnt ligands, Wnt1 and Wnt4 are the most widely recognized to contribute to the pathogenesis of renal fibrosis." (PMID 34122087, 2021). "Conditional expression of Wnt1 in the proximal tubules effectively activated fibroblasts and promoted renal fibrosis." (PMID 33434361, 2021). "Additionally, in vivo expression of exogenous Wnt1 at 3 days before renal unilateral IR inhibited endogenous Wnt/β-catenin signaling and prevented the development of renal fibrosis in CKD mice (11 days after IR)." (PMID 34819873, 2021). "In addition, compared with the UUO group, the levels of Wnt1, active β-catenin, Snail1, and PAI-1 expression were reduced in the SKI group, suggesting that SKI may reduce renal fibrosis by mediating the Wnt/β-catenin pathway." (PMID 35800011, 2022). "Notably, the observed alterations of serum kidney injury biomarkers and renal fibrosis in CKD mice were almost completely prevented by pre-treatment of exogenous Wnt1, but not ICG-001." (PMID 34819873, 2021).
cervical cancer (7 papers, 2020 to 2025). A primary or metastatic malignant neoplasm involving the cervix. "Additionally, our findings strongly suggest that LMP2 and TAP2’s effects on cell growth, proliferation, and tumor growth in cervical cancer are closely associated with the modulation of Wnt1 expression." (PMID 37986152, 2023). "To investigate whether Wnt1 is indeed required for the observed phenotypes caused by NEK2 silencing in cervical cancer cells, we transfected exogenously expressed Wnt1 into NEK2-depleted cells." (PMID 32907622, 2020). "Importantly, our rescue results showed that the biological effects caused by NEK2 knockdown are mainly dependent on Wnt1 in cervical cancer cells." (PMID 32907622, 2020). "It is reported that the knockdown of NEK2 can reduce the expression of Wnt1 and β-catenin to subvert the oncogenesis of cervical cancer cells." (PMID 37986152, 2023). "Targeting NEK2 inhibits tumorigenesis through the Wnt1/beta-catenin signaling pathway in cervical cancer." (PMID 36499051, 2022). "To investigate the role of WNT1 in cervical cancer development, we first assessed the level of WNT1 expression in HPV-16 positive Siha and Caski cells and HPV-negative C33A cells." (PMID 32301035, 2020). "More importantly, the observed consequences induced by NEK2 depletion in cervical cancer cells can be partially rescued by Wnt1 overexpression." (PMID 32907622, 2020). "Accordingly, these results reveal that NEK2 exerts its biological functions mainly via regulating Wnt1 in cervical cancer." (PMID 32907622, 2020). "Consequently, these findings indicate that the primary mechanisms through which LMP2 and TAP2 exert their biological effects in cervical cancer predominantly involve the regulation of Wnt1." (PMID 37986152, 2023). "In our study, we identified Wnt1 as a key downstream effector of NEK2 in cervical cancer." (PMID 32907622, 2020). "Moreover, we for the first time show that NEK2 upregulates Wnt1 to activate Wnt/β-catenin signaling pathway, thereby promoting oncogenesis and radioresistance in cervical cancer." (PMID 32907622, 2020). "Our findings indicate that targeting NEK2/Wnt1/β-catenin pathway may be a potential radiosensitization strategy in cervical cancer." (PMID 32907622, 2020). "Furthermore, we exogenously upregulated the expression of miR-34a in cervical cancer cell lines and found, both in vitro and in vivo, that the mRNA and protein levels of WNT1 were significantly decreased." (PMID 32301035, 2020). "We, therefore, set out to evaluate whether miR-34a may target the WNT1/β-catenin pathway and, subsequently, induce an E-P cadherin switch during cervical cancer development regulated by HPV-16 E6/E7." (PMID 32301035, 2020). "In cervical cancer, NEK2 activates β-catenin signaling by promoting wnt1 expression, enhancing cell resistance to radiotherapy." (PMID 38503948, 2025). "Accordingly, our work uncovered that NEK2 is a novel positive modulator of Wnt1 and provided new insights into the molecular mechanisms by which NEK2 participates in oncogenesis and radioresistance in cervical cancer." (PMID 32907622, 2020). "In addition, Wnt1 overexpression partially rescued the observed consequences of ectopic expression of LMP2 and TAP2 in cervical cancer cells." (PMID 37986152, 2023). "To explore whether the presence of Wnt1 is indeed necessary for the observed effects resulting from the overexpression of LMP2 and TAP2 in cervical cancer cells, we introduced exogenous expression of Wnt1 into LMP2 and/or TAP2 overexpressed cells." (PMID 37986152, 2023). "Our results demonstrate that NEK2 activates the Wnt/β-catenin signaling pathway via Wnt1 to drive oncogenesis and radioresistance in cervical cancer, indicating that NEK2 may be a promising target for the radiosensitization of cervical cancer." (PMID 32907622, 2020).
cervical cancer (continued). "Importantly, we show that NEK2 depletion impairs cervical cancer progression and radioresistance in a Wnt1-dependent manner, indicating that NEK2 may be a promising target for cervical cancer radiotherapy." (PMID 32907622, 2020).
liver cancer (7 papers, 2014 to 2025). An epithelial or non-epithelial malignant neoplasm that arises from the liver. "The histograms show Wnt1 expression in liver cancer cells while treating with different materials, showing that in the overall studies, compared with the control, the expression was less in all the treated groups." (PMID 39610791, 2025). "We confirmed that Wnt1, LEF, and β-catenin-positive cell populations were significantly increased in human liver cancer tissues." (PMID 26967248, 2016). "Therefore, to determine whether Wnt/β-catenin signaling is implicated in hepatocarcinogenesis, we examined the expression of Wnt/β-catenin signaling components, including Wnt1, LEF, and TCF4, in tissue samples from liver cancer patients." (PMID 26967248, 2016).
lung adenocarcinoma (7 papers, 2012 to 2024). A carcinoma that arises from the lung and is characterized by the presence of malignant glandular epithelial cells. "For example, Wnt3a and Wnt5a are expressed at higher levels in melanoma, whereas Wnt1 is highly expressed in lung adenocarcinoma." (PMID 32132993, 2020). "Altering Wnt1 expression profoundly affects growth of murine lung adenocarcinomas and this is dependent on conventional dendritic cells (cDCs) and T cells." (PMID 30926812, 2019). "Ex vivo assays with primary human LUAD cells and models of lung adenocarcinoma show that Wnt1 impairs cross-priming of T cytotoxic cells and induces T cell exclusion from tumors via cDCs." (PMID 30926812, 2019). "Likewise, neutralizing or silencing Wnt1 in lung adenocarcinoma model augmented DC activation, resulting in increased recruitment and accumulation of CTLs in the TME." (PMID 32132993, 2020). "Here, the authors show that, in lung adenocarcinoma, secretion of the ligand Wnt1 induces immune resistance by impairing the ability of dendritic cells to cross-prime T cells, and that blocking Wnt signalling enhances rejection of tumours by acting both on the cancer and immune cells." (PMID 30926812, 2019). "Autochthonous murine tumors may more closely recapitulate human tumor–host interactions, so we validated Wnt1 as immunotherapeutic target in autochthonous lung adenocarcinomas." (PMID 30926812, 2019). "circFOXP1 expression was increased in lung adenocarcinoma (LUAD) and promoted cell proliferation by interacting with the miR-185-5p and regulating WNT1 expression in LUAD27." (PMID 38745044, 2024). "Although the A549 cell line is a human-derived lung adenocarcinoma cell line, it is widely used to establish an EMT model by stimulating the cells with Wnt-1 or other cytokines because its morphology and basic cell functions are similar to those of human alveolar type II epithelial cells." (PMID 34563177, 2021). "To substantiate a specific role for human Wnt1 in b-catenin activation in intratumoral cDCs, we cultured dissociated primary lung adenocarcinomas in the presence or absence of siWnt1 RNA." (PMID 30926812, 2019). "In addition, obviously higher expression of oncogenes c-MYC, WNT1, WNT2, and NOTCH1 was detected in side population (SP) cells than in non-side population (NSP) cells of human lung adenocarcinoma cell line-A549, revealing a possible mechanism for the tenacious tumorigenic potential of CSCs." (PMID 22615765, 2012).
pancreatic cancer (7 papers, 2020 to 2025). "Moreover, miR 148a‐3p suppresses the proliferation, invasion, and stemness characteristics of pancreatic cancer cells by inhibiting the Wnt1/β‐catenin pathway, which is controlled by Wnt1." (PMID 39812156, 2025). "Moreover, another research group showed that, in pancreatic cancer, miR-148a-3p inhibits the epithelial–mesenchymal transition and stemness properties via the Wnt1-mediated Wnt/-catenin pathway." (PMID 37628628, 2023).
sarcoma (7 papers, 2005 to 2025). A usually aggressive malignant neoplasm of the soft tissue or bone. "We treated cell lines A-204, SJSA-1, and fresh primary cultures of lung metastasis of sarcoma with a monoclonal anti-Wnt-1 antibody." (PMID 15913453, 2005). "We treated A-204, SJSA-1 cells and fresh primary cultures with the monoclonal anti-Wnt-1 antibody after confirmation of Wnt-1/β-catenin signaling in sarcoma cells." (PMID 15913453, 2005). "Next, the monoclonal anti-Wnt-1 antibody was utilized for treating the sarcoma cell lines A-204 and SJSA-1." (PMID 15913453, 2005). "The expression of Wnt-1, Dvl-1, 2, 3 and cytosolic β-catenin was analyzed in 6 tissue samples of metastatic sarcoma, A-204 and SJSA-1 cell lines." (PMID 15913453, 2005). "Our results indicate that Wnt-1 blockade by either monoclonal antibody or siRNA induces cell death in sarcoma cells." (PMID 15913453, 2005). "Moreover, they treated sarcoma cell lines and fresh primary cultures with a monoclonal anti-WNT-1 antibody." (PMID 34771683, 2021). "An antibody to WNT1 induced cell death in sarcoma cells including OS." (PMID 25992885, 2015). "Furthermore, the monoclonal anti-Wnt-1 antibody also induced cell death in fresh primary cultures of metastatic sarcoma in which Wnt-1 signaling was active." (PMID 15913453, 2005). "Our results indicate that the monoclonal anti-Wnt-1 antibody induces cell death in sarcoma cells." (PMID 15913453, 2005). "In the present study, we address this hypothesis and demonstrate a possible therapeutic role of this monoclonal anti-Wnt-1 antibody in the treatment of sarcoma cells." (PMID 15913453, 2005). "In this study, we investigated the efficacy of a monoclonal anti-Wnt-1 antibody in sarcoma cells." (PMID 15913453, 2005). "In summary, our work shows that EMX1 and EMX2 act as tumor suppressors by suppressing the activity of stem cell regulatory genes (OSKM, NANOG, and PROM1) and effectors of the canonical Wnt pathway (CTNNB1, TCF4, MYC, WNT1 and CCDN1) in sarcoma." (PMID 34364391, 2021). "In sarcoma cells, we found reductions in the protein levels of positive effectors of the Wnt pathway (β-catenin, TCF4, c-MYC and WNT1) and increases in those of negative effectors (GSK3-β and AXIN1) in cells overexpressing EMX proteins." (PMID 34364391, 2021).
diabetes (6 papers, 2012 to 2023). "Wnt1 also prevents protects against cell loss in dopaminergic neurons in models of Parkinson’s disease, limits vascular injury during experimental diabetes, maintains microglial cell survival during Aβ exposure." (PMID 23109841, 2012). "Wnt1 has previously been shown to activate the PI 3-K/Akt1 pathway during serum deprivation, ischemic injury, experimental diabetes as well as tumor growth." (PMID 22388478, 2012). "In models of experimental diabetes, EPO preserves brain EC integrity that is necessary for protection of the neurovascular unit through Wnt1, since administration of anti-Wnt1 neutralizing antibodies or gene silencing of Wnt1 block EPO protection." (PMID 23109841, 2012). "Wnt1 and the wingless pathway offer cellular protection through non-neuronal cells including microglia and mediate EPO cytoprotection in experimental models of diabetes mellitus and hypoxia." (PMID 22388478, 2012).